INS (insulin)
Diseases named in the same sentence as INS in open-access papers (continued):
Sharing a sentence is not in itself a finding about the gene and the disease.
diabetes (continued). "To study the function of PI4KIIα in T2DM and insulin secretion, we first investigated PI4KIIα expression levels in mouse models of diabetes." (PMID 29577067, 2018). "Altogether, this alternative model, involving both insulin resistance and beta cell dysfunction, is useful for studying the pathogenesis of diabetes complications, such as diabetic cardiomyopathy, nephropathy, neuropathy and retinopathy." (PMID 29323186, 2018). "Pancreatic islet transplantation is a promising treatment for type 1 diabetes mellitus offering improved glycaemic control by restoring insulin production." (PMID 30347797, 2018). "Although G. officinalis reduces glucose concentration in blood of patients with diabetes, the search for its active compound has been slow, primarily due to the effects of light on this plant and the introduction of insulin." (PMID 30208162, 2018). "The authors wish to express their gratitude to the Insulin-Dependent Diabetes Trust (IDDT), Northampton, U.K., for their generous support." (PMID 29615978, 2018). "During the past decades, many advances in routine therapy of type 1 diabetes have been achieved, for example, use of insulin pumps, glucose sensors, insulin analogues, or intensified diabetes education and psychosocial support." (PMID 29808091, 2018). "Insulin sensitivity was 14% and beta cell function 71% (both p < 0.001) lower in type 2 diabetes mellitus patients." (PMID 30190473, 2018). "Both T1DM and T2DM patients had a similar duration of diabetes (both with a median of 15.0 years) but T1DM patients had a longer duration of insulin use (median of 14.0 years vs. 6.0 years)." (PMID 30479669, 2018). "We find that application of PIO, a common insulin sensitizer used in diabetes therapy, can significantly alter the GABAA receptor response and restore E/I balance to levels of normalcy." (PMID 29484150, 2018). "Our study proposes therapeutic roles for androgen signaling in diabetes and, more broadly, offers a novel in vivo model for rapid screening and decoupling of insulin-dependent and -independent mechanisms." (PMID 30520733, 2018). "Between 1980 and 2000 the insulin pumps became smaller and portable, while the models of the glucose-insulin system became larger and more elaborate, allowing first computer simulation and then automated model-predictive glucose control of diabetes." (PMID 32232090, 2018). "Alterations in serum lipid profiles are known in diabetics, probably due to increase in the mobilization of free fatty acids from the peripheral depots, as insulin inhibits the hormones lipase (Radhika, Smila, & Muthezhilan, 2011)." (PMID 29387371, 2018). "Increased insulin resistance (IR) and deteriorated insulin secretion (ISEC) are considered to be the main mechanisms in type 2 diabetes mellitus (T2DM) development." (PMID 29377927, 2018). "In the only clinical trial conducted to date, proinsulin was tested as a possible insulin agonist of intermediate-acting effect for the treatment of diabetes mellitus." (PMID 30534050, 2018). "Thus, further research is required to elucidate how certain exercise regimens can promote tissue-specific adaptations in insulin-signaling and how these pathways may be targeted to reverse insulin-resistance and associated cardiovascular complications of diabetes." (PMID 30324108, 2018). "Diabetes patients must control their blood glucose level very strictly and many need to inject insulin on a regular basis." (PMID 29731775, 2018). "Diabetes treatments varied, although majority of the participants were using intensive insulin management (85%, 155/183)." (PMID 30291079, 2018). "Variables that were significant predictors after univariate testing were included in the model as independent variables (sex, age, insulin regimen, insulin rate per kg, duration of diabetes, ACARFS score, percent of dietary energy total fat intake)." (PMID 29549246, 2018).
diabetes (continued). "Two types of diabetes are common among humans: type 1 diabetes that occurs when the immune system attacks and destroys insulin." (PMID 29507651, 2018). "The games typically involve players in problem-solving and decision-making in simulations of diabetes self-management, usually by asking players to balance food intake and insulin injections to keep a game character’s blood glucose within a normal range." (PMID 29385750, 2018). "The G allele of rs10830963 confers risk of diabetes mellitus through a stage of isolated-IFG and a decrease of oral and intravenous glucose-stimulated insulin release, suggesting a pancreatic β-cell dysfunction and a decreased acute serum insulin response." (PMID 30477160, 2018). "Alloxan monohydrate caused the destruction of β –cells and stops the production of Insulin and results in induction of diabetes." (PMID 29463309, 2018). "FTO was previously shown to be involved in several metabolic syndrome-related conditions such as diabetes, insulin signaling, lipogenesis, and mitochondrial dysfunction, whereby FTO overexpression was observed." (PMID 29922517, 2018). "We found that patients treated with insulin were more likely to develop foot ulcer than were patients whose diabetes is managed with oral glycemic agent or lifestyle modification alone." (PMID 29736169, 2018). "Diabetes is driven by impaired insulin action (insulin resistance) and insulin secretion (islet dysfunction and incretin failure), co-influenced by genetics and environment." (PMID 29549240, 2018). "To further define the relationship between CAC-3 levels and diabetes, we determined associations between the low CAC-3 count group and HbA1c (> 5.6%), fasting plasma glucose, HOMA-IR, and insulin." (PMID 30321232, 2018). "We found that after six weeks of intervention, mice treated with ketogenic diet and ketogenic diet combined with exercise both have lower body weights, HbAlc level, HOMA index, and improvements in insulin sensitivity, compared with diabetes group." (PMID 29743883, 2018). "The vast majority of CHI patients with diabetes were treated with insulin (85.2% at diabetes onset, and 90.5% at follow-up)." (PMID 30577875, 2018). "The second is, do patients who develop ketosis-prone diabetes have unique abnormalities of beta cell function and/or insulin resistance that are part of their metabolic regulatory systems." (PMID 30280274, 2018). "Little is known about diabetes/insulin exposure and protein signaling in tumors in the human setting." (PMID 29486734, 2018). "The mean duration of diabetes and the percentage of subjects who received diabetic medication including oral hypoglycemic agents and/or insulin therapy were 13.4 ± 8.8 years and 84.3%, respectively." (PMID 29494595, 2018). "Patients with diabetes were all treated with oral antidiabetics at baseline, and two were additionally on insulin." (PMID 30109666, 2018). "Prolactin (PRL) is known to directly increase β-islet cell insulin secretion and PRL level has been recently linked to deficient glucose regulation and the state of diabetes itself." (PMID 29975740, 2018). "Insulin levels were higher in IFG than in previously diagnosed diabetes participants (P < 0.001), whereas HOMA-IR levels were the opposite (P < 0.001)." (PMID 30211231, 2018). "Many blamed themselves for having to initiate insulin therapy and reported high degrees of diabetes distress." (PMID 30116737, 2018). "When these insulin-producing cells were transplanted into immunodeficient mice that had developed streptozotocin (STZ)-induced diabetes, hyperglycemia decreased dramatically, so that the mice become normoglycemic." (PMID 30594258, 2018). "Despite many anti-hyperglycemic agents, a considerable number of patients with type 2 diabetes mellitus (T2D), including those treated with basal-bolus insulin therapy, have sub-optimal glycemic control." (PMID 30410846, 2018).
diabetes (continued). "Four years later, anti-GAD65 and anti-insulin antibody-positive insulin-dependent diabetes mellitus was recognized." (PMID 30087679, 2018). "Further support for an initiating role for HI is the ability to predict diabetes in subjects with high plasma insulin concentrations among Pima Indians." (PMID 30271382, 2018). "The increasing morbidity of type 2 diabetes mellitus has necessitated a search for new types of therapeutic agents with the ability to stimulate the release of insulin." (PMID 29360748, 2018). "As expected, in this study, we demonstrated that first-phase insulin secretion was partially restored after normalizing blood glucose with SIIT in patients of varying diabetes duration." (PMID 30581872, 2018). "If a patient is suffering from insulin-dependent types of diabetes mellitus, he or she needs to regulate his blood sugar levels via subcutaneous injections of insulin multiple times each day." (PMID 30394120, 2018). "In contrast, The Joint British Diabetes Societies Inpatient Care Group recommends a fixed rate IV insulin infusion of 0.1 units/kg/h, and advises against the use of an initial insulin bolus in the 2013 guidelines." (PMID 30544554, 2018). "A high susceptibility to the development of fluid retention has been attributed to T2DM subjects with advanced age, longstanding diabetes, insulin treatment, pre-existing edema, established cardiovascular disease and CKD." (PMID 30379936, 2018). "This places the adolescent population at increased risk of having nutritionally inadequate intakes, and has significant implications for the optimisation of their insulin therapy and overall diabetes treatment." (PMID 29549246, 2018). "This is in line with reports showing that BCAAs already increase in an early obesity-induced insulin-resistant state before the onset of diabetes." (PMID 29854816, 2018). "Patient attitudes after hypoglycemia, such as reduction in insulin and increase in calorie intake, can affect diabetes management." (PMID 30479669, 2018). "In contrast, a single dose 40 IU of intranasal insulin in patients with diabetes was found to improve cerebral blood flow and visuospatial memory." (PMID 30515210, 2018). "Zimbabwean adults with diabetes mellitus have knowledge gaps regarding diet, glycemic control and insulin use." (PMID 30050608, 2018). "There were comments that in clinic, the focus tends to be on blood glucose and insulin doses whilst ADNAT promoted reflection on all aspects of their diabetes, including their feelings." (PMID 28694992, 2018). "Increased insulin production in turn prompts beta cell stress, as the cells are not able to cope with elevated insulin demand leading to the onset of diabetes." (PMID 30297648, 2018). "Type 2 diabetes (T2D) was determined by: self-reported diabetes, current anti-diabetic drug use (insulin/oral hypoglycemic agents), fasting glucose (≥126 mg/dL), or non-fasting glucose (≥200 mg/dL)." (PMID 30513871, 2018). "The treatment of diabetes mainly depends on hypoglycemic drugs such as insulin, sulfonylurea, metformin, α-glucosidase inhibitor, and thiazolidinediones, by increasing the insulin level, enhancing the insulin sensitivity, or decreasing the glucose absorption." (PMID 30301245, 2018). "For many patients it is possible to switch insulin preparation or to avoid insulin use by managing their diabetes through diet or oral antidiabetics and/or injections with glucagon-like peptide 1 (GLP1) analogue treatment." (PMID 30258565, 2018). "Further researches on how animal and plant components affect β-cell function and insulin resistance will be needed to establish the ideal diet for diabetes prevention." (PMID 29549240, 2018). "Although insulin and other artificially synthesized anti-diabetes drugs like acarbose and voglibose are effective for the management of diabetes, they are far from satisfying the urgency for their enormous costs or undesirable side effects." (PMID 29710864, 2018).
diabetes (continued). "Diabetes mellitus (DM) is a chronic hyperglycemic disease condition attributed to defective insulin secretion or action or both." (PMID 30170601, 2018). "Diabetes is a complex disease that requires not only adherence to medications (including insulin regimens and oral drugs) but also to diet, physical exercise and home glucose monitoring, among others." (PMID 29636825, 2018). "Respondents answered that they recommend the portal to most of their patients, but especially to patients with type 1 diabetes mellitus, patients on insulin therapy, younger and higher educated patients." (PMID 29929483, 2018). "Meanwhile, the decreased half-life of circulating insulin in hyperthyroidism aggravates the pancreas burden and diabetes." (PMID 30013597, 2018). "Understanding of the regulatory mechanisms of critical transcriptional factors, such as Ngn3, NeuroD1, and Insm1, in islet development is important for making insulin-producing cells for prospective stem cell therapy to treat diabetes." (PMID 30359270, 2018). "Insulin is a vital part of diabetes treatment, whereas glucagon is primarily used to treat insulin-induced hypoglycemia." (PMID 29558502, 2018). "In the current study, we designed a flow cytometric approach to detect live, insulin-producing β cells to evaluate PD-L1 expression during diabetes pathogenesis." (PMID 29844327, 2018). "The expression levels of SeP in the liver are positively correlated with the severity of insulin resistance in diabetes, and SeP is known to reduce insulin-induced Akt phosphorylation in both liver and skeletal muscle in mice." (PMID 29547524, 2018). "In recent years, epidemiological studies suggest that diabetes mellitus is a risk factor for Alzheimer’s disease, which may include three common pathological properties as follows, cerebrovascular inflammation, amyloid deposition, and impairment of brain insulin signaling." (PMID 30072873, 2018). "This feasibility study of the effect of diabetes-specific formulae on the administration of insulin in critically ill patients and will inform the design of a larger, multi-center trial." (PMID 29631990, 2018). "As our findings have illustrated, some diabetes management tasks, such as counting carbohydrate contents in meals and determining insulin doses, were too difficult for children in this age group to do independently even if they were motivated to do so." (PMID 30316299, 2018). "β-cell failure, a result of the progressive decline in pancreatic β cell function and mass, impairs insulin secretion and contributes to the development of type 2 diabetes mellitus." (PMID 29558390, 2018). "Frequent and precise blood glucose monitoring and concomitant optimal adjustment of insulin to carbohydrate intake and exercise are the basis of diabetes treatment." (PMID 29527102, 2018). "STR was highest for patients less than 70 years of age, males, patients with longer duration of diabetes, patients taking insulin, patients with higher A1c or missing A1c data in the IHS-JVN record, and patients imaged with UWFI." (PMID 29924846, 2018). "Diabetes mellitus results from either autoimmune destruction of insulin producing beta cells of the pancreas or insulin resistance, a condition in which cells fail to properly use insulin." (PMID 30285833, 2018). "Subjects with IR will progress to overt diabetes if β-cells fail to secrete adequate amounts of insulin to compensate for the defects in its action." (PMID 29614722, 2018). "Type 1 diabetes mellitus (T1DM) is defined as an autoimmune disease that targets the selective destruction of islet insulin-producing beta cells by infiltrating immune cells (insulitis)." (PMID 31225479, 2018). "Nevertheless, when these insulin-positive cells were transplanted into immunodeficient mice, they were able to mature further and demonstrated successful signs of curing diabetes in these mice." (PMID 29963051, 2018).
diabetes (continued). "Horvath K, Jeitler K, Berghold A, Ebrahim SH, Gratzer TW, Plank J, Kaiser T, Pieber TR, Siebenhofer A. Long‐acting insulin analogues versus NPH insulin (human isophane insulin) for type 2 diabetes mellitus." (PMID 29527102, 2018). "In fact, in a recent study of the db/db mouse model of diabetes, loss of ELOVL6 alters insulin sensitivity and the expression of ER stress genes." (PMID 30081392, 2018). "Age, preoperative dialysis, aortic cross-clamp time in upper quartile (≥ 62min), moderate to severe LV dysfunction, NYHA IV, insulin-treated diabetes, critical preoperative state, and emergency operation were the other variables in the final model." (PMID 29420603, 2018). "Diabetes mellitus is one of a major worldwide concerns, regulated by either defects in secretion or action of insulin, or both." (PMID 29546042, 2018). "What dictates the type of treatment needed/required for diabetes, and is directly injecting insulin ever avoidable?" (PMID 30444868, 2018). "Epidemiological studies in non-pregnant adults have demonstrated associations between phthalates and raised fasting blood glucose, insulin resistance, reduced insulin secretion, and type 2 diabetes mellitus (T2DM)." (PMID 29593656, 2018). "Diabetes mellitus (DM) is a chronic metabolic disorder in which the body’s ability to produce or respond to the hormone insulin is impaired, resulting in abnormal metabolism of carbohydrates and elevated levels of glucose in the blood and urine." (PMID 29805204, 2018). "In diabetes patients on intensive insulin regimens, SMBG is suggested at premeals, during snack, and bedtime, occasionally after eating, preexercise, when suspicion of and after correction of hypoglycemia, and before tasks like driving." (PMID 29527102, 2018). "β-cell dysfunction precedes diabetes, and endoplasmic reticulum (ER) stress contributes to insulin secretory failure." (PMID 29867762, 2018). "The absence of both hypoglycaemia and weight gain reflect that endogenous insulin secretion is tightly regulated in patients with permanent neonatal diabetes." (PMID 29880308, 2018). "Pen needles are an important component of insulin delivery among insulin-requiring patients with diabetes." (PMID 29699587, 2018). "Further studies evaluating the impact of SGLT2 inhibition on insulin sensitivity, NO, and functional exercise capacity in diabetes are warranted." (PMID 29720965, 2018). "Particularly, regulation of insulin secretion from pancreatic β-cell is considered as targets for diabetes therapies." (PMID 29950956, 2018). "Our work shows 3.5-fold and 3.9-fold increased odds of developing diabetes mellitus (type 1 and 2) in women with autism and PCOS, respectively, suggesting a close association of both with insulin and insulin resistance." (PMID 30065244, 2018). "Diabetes mellitus is a metabolic syndrome characterized by chronic high-blood glucose concentrations resulting from defects in insulin secretion, insulin action or both and having consequences on lipids and proteins metabolism." (PMID 30574237, 2018). "Among 4 study participants identified to have HNF1A-MODY and treated with insulin, 2 were changed from insulin to an SU treatment and their diabetes remains well controlled." (PMID 29666556, 2018). "Hypoglycemia in diabetes involves a combination of therapeutic insulin excess and compromised physiologic defense." (PMID 29473001, 2018). "One large Dutch survey observed that the more structured practices employing a PN and with a designated diabetes clinic were more likely to manage insulin therapy themselves." (PMID 29788908, 2018). "Patients referred to the service, are provided with a handheld device called d-Nav (stands for diabetes navigator) which advises them what dose of insulin to administer during each injection." (PMID 29682315, 2018).